AJUBA (ajuba LIM protein)
Description:
Adapter or scaffold protein which participates in the assembly of numerous protein complexes and is involved in several cellular processes such as cell fate determination, cytoskeletal organization, repression of gene transcription, mitosis, cell-cell adhesion, cell differentiation, proliferation and migration. Contributes to the linking and/or strengthening of epithelia cell-cell junctions in part by linking adhesive receptors to the actin cytoskeleton. May be involved in signal transduction from cell adhesion sites to the nucleus. Plays an important role in regulation of the kinase activity of AURKA for mitotic commitment. Also a component of the IL-1 signaling pathway modulating IL-1-induced NFKB1 activation by influencing the assembly and activity of the PRKCZ-SQSTM1-TRAF6 multiprotein signaling complex. Functions as an HDAC-dependent corepressor for a subset of GFI1 target genes. Acts as a transcriptional corepressor for SNAI1 and SNAI2/SLUG-dependent repression of E-cadherin transcription. Acts as a hypoxic regulator by bridging an association between the prolyl hydroxylases and VHL enabling efficient degradation of HIF1A. Positively regulates microRNA (miRNA)-mediated gene silencing. Negatively regulates the Hippo signaling pathway and antagonizes phosphorylation of YAP1.
Synonyms: JUB; MGC15563
Tractability: Antibody: UniProt places it where antibodies can reach, with medium confidence; its Gene Ontology location is reachable by antibodies, with medium confidence. PROTAC: ubiquitination databases record sites on it.
Gene: Protein-coding gene on chromosome 14 (22,971,177 to 22,982,551, reverse strand). Ensembl gene ENSG00000129474.
Subcellular location: Cytoplasm, cytoskeleton; Cell membrane; Cell junction; Nucleus; Cytoplasm, cytoskeleton, microtubule organizing center, centrosome; Cytoplasm, P-body
Subcellular location (Human Protein Atlas): Golgi apparatus; Nucleoplasm
Pathways (Reactome):
Cell Cycle: Regulation of PLK1 Activity at G2/M Transition
Cellular responses to stimuli: Oxygen-dependent proline hydroxylation of Hypoxia-inducible Factor Alpha
Developmental Biology: Activation of anterior HOX genes in hindbrain development during early embryogenesis
Gene expression (Transcription): MLL4 and MLL3 complexes regulate expression of PPARG target genes in adipogenesis and hepatic steatosis
Gene Ontology:
Molecular function: alpha-catenin binding; protein binding; transcription corepressor activity; actin filament binding; chromatin binding; protein kinase activator activity
Biological process: miRNA-mediated gene silencing by inhibition of translation; miRNA-mediated post-transcriptional gene silencing; negative regulation of hippo signaling; positive regulation of protein-containing complex assembly; regulation of cellular response to hypoxia; response to hypoxia; cytoskeleton organization; regulation of DNA-templated transcription; negative regulation of DNA-templated transcription; positive regulation of canonical NF-kappaB signal transduction
Cellular component: cell-cell junction; nucleus; P-body; adherens junction; cytosol; transcription regulator complex; anchoring junction; centrosome; cytoskeleton; focal adhesion; lamellipodium; plasma membrane
Genetic constraint (gnomAD): Loss-of-function variants: 20 observed, 49.99 expected, observed/expected ratio (o/e) 0.4, 90% interval 0.28 to 0.58. The upper end of that interval is the gene's LOEUF score, 0.58, which puts it in group 2 of 6, group 1 being the genes least tolerant of losing a copy. Missense variants: 580 observed, 689.25 expected, observed/expected ratio (o/e) 0.84, 90% interval 0.79 to 0.9. Synonymous variants: 296 observed, 283.41 expected, observed/expected ratio (o/e) 1.04, 90% interval 0.95 to 1.15.
Homologues: Orthologues: chimpanzee AJUBA (100% identical), macaque AJUBA (99% identical), pig AJUBA (96% identical), guinea pig AJUBA (94% identical), mouse Ajuba (93% identical), rat Ajuba (93% identical), dog AJUBA (91% identical), zebrafish ajuba (48% identical). Paralogues in human: WTIP (34% identical), LIMD1 (33% identical).
Diseases named in the same sentence as AJUBA in open-access papers:
AJUBA is named in the same sentence as 50 diseases in open-access papers, as found by Europe PMC text mining. Sharing a sentence is not in itself a finding about the gene and the disease. The quoted sentences say what the papers report.
colorectal cancer (14 papers, 2016 to 2025). A primary or metastatic malignant neoplasm that affects the colon or rectum. "Finally, AJUBA was found as being associated with cell migration in colorectal cancer." (PMID 38993634, 2024). "AJUBA promotes colorectal cancer (CRC) growth by inhibiting apoptosis.AJUBA has also been shown to stimulate breast cancer cell growth, invasion, chemoresistance and glucose uptake." (PMID 40240814, 2025). "AJUBA expression is higher in colorectal cancer (CRC) tissues than normal tissues, but its specific molecular function in CRC progression is still not very clear." (PMID 36931700, 2023). "Previous studies have shown that the AJUBA protein promotes colorectal cancer cell growth by suppressing the JAK1/STAT1/IFIT2 network and activating N-cadherin expression through interaction with Twist in colorectal cancer cells." (PMID 37765273, 2023). "Recent studies have demonstrated that NFATC2 promotes the stemness of colorectal cancer stem cells via AJUBA-mediated YAP activation and constitutes a novel therapeutic target." (PMID 37601778, 2023). "For example, the LIM protein AJUBA promotes the growth of colorectal cancer cells via suppression of the JAK1/STAT1/IFIT2 network and activates N-cadherin expression through interaction with Twist in colorectal cancer cells." (PMID 35898403, 2022). "For instance, NFATc2 promoted cancer stemness of colorectal cancer via AJUBA-mediated YAP activation." (PMID 36077186, 2022). "The binding relationship between hsa_circ_0128846, miR‐1184 and AJUBA mRNA in colorectal cancer was validated by reported gene assay." (PMID 32681581, 2020). "In colorectal cancer tissues, circ_0128846 and AJUBA were both significantly up‐regulated, while miR‐1184 was significantly down‐regulated compared with healthy tissues." (PMID 32681581, 2020). "In addition to, overexpression of AJUBA promotes tumorigenesis of colorectal cancer by inactivating Hippo signaling." (PMID 35898403, 2022). "Besides, CircCSPP1 could promote tumorigenesis of colorectal cancer by sponging hsa-miR-1184 and releasing AJUBA and inactivating Hippo/YAP signaling." (PMID 33663510, 2021). "Several studies have demonstrated that AJUBA expression has a positive correlation with the EMT process in different cancers, including in colorectal cancer and hepatocellular carcinoma." (PMID 35898403, 2022). "Mechanistically, both transcriptional activation of the P-body-related genes SAMD4A, AJUBA, and WTIP and transcriptional suppression of the tumor suppressor gene PNRC1 are involved in enhancing the effects of YAP/TAZ on P-body formation in colorectal cancer (CRC) cells." (PMID 39046443, 2024).
hepatocellular carcinoma (5 papers, 2022 to 2025). A malignant tumor that arises from hepatocytes. "Analogously, AJUBA, an oncogenic protein regulated by SE and linked to an unfavorable prognosis, engages TRAF6 to facilitate the activation of AKT signaling in hepatocellular carcinoma (HCC)." (PMID 38844984, 2024).
breast carcinoma (4 papers, 2022 to 2025). "Afterwards, we made use of the CPTAC database to analyze the molecular mechanism of the AJUBA protein in breast cancer, ovarian cancer, colon cancer, LUAD, clear cell RCC, and UCEC in the field of total and phosphorylated proteins." (PMID 35898403, 2022). "Previous research has found that AJUBA expression is related to poor prognosis in HCC, CRC, breast cancer and esophageal squamous cell carcinoma, but the impact of AJUBA on the survival rate in lung cancer has not been reported." (PMID 40240814, 2025). "Next, we confirmed the significantly downregulated mRNA expression of AJUBA, WTIP, SAMD4A, and NOCT and moderately increased expression of PNRC1 in YAP/TAZ knockdown HCT116 cells by qPCR analysis; this pattern was also observed in A549 lung cancer cells and MDA-MB-231 breast cancer cells." (PMID 39046443, 2024). "In the BRCA samples of TCGA, we also noticed a significant relationship between AGR2 expression and FOXA1 gene copy number, as well as several cancer gene copy numbers localized at 14q such as NFKBIA, SAV1, CHD8 or AJUBA, which are not known as driver oncogenes or TSG in breast cancer." (PMID 35857928, 2022).
colon cancer (4 papers, 2019 to 2022). "The TCGA results indicated that SPIB, KRT24, PHLPP2, PLP1, BEST4, CA7, and C11orf86 were all downregulated, while KRT80, SLC39A10, AJUBA, FOXQ1, and CLDN1 exhibited upregulated levels in colon cancer." (PMID 32633726, 2020). "The KEGG analysis revealed correlations of AJUBA, CLDN1, and PHLPP2 with signaling pathways related to the occurrence and progression of colon cancer." (PMID 32633726, 2020). "Moreover, AJUBA is phosphorylated by CDK1, controls multiple cell cycle regulators, and promotes cell proliferation and tumorigenesis of colon cancer." (PMID 30690883, 2019).
head and neck squamous cell carcinoma (4 papers, 2016 to 2018). A squamous cell carcinoma that arises from any of the following anatomic sites: lip and oral cavity, nasal cavity, paranasal sinuses, pharynx, larynx, and salivary glands. "Increasing evidence, including the detection of AJUBA mutations in multiple human cancers such as ESCC, cutaneous squamous cell carcinoma and head and neck squamous cell carcinomas, suggests a role for AJUBA in tumorigenesis." (PMID 27172796, 2016).
cervical cancer (3 papers, 2019 to 2022). A primary or metastatic malignant neoplasm involving the cervix. "Another study showed that Ajuba LIM Protein (AJUBA) negatively regulated the Hippo signaling pathway and increased the resistance of cervical cancer cells to cisplatin, which is also associated with reduced survival time." (PMID 35094292, 2022). "AJUBA is an oncoprotein reported to negatively regulate the Hippo kinase LATS1, and the inhibition of LATS1 by AJUBA induces YAP activation in cervical cancer and CRC." (PMID 35885009, 2022). "AJUBA is highly expressed and confers cisplatin resistance on cervical cancer cells." (PMID 31262974, 2019).
lung carcinoma (3 papers, 2019 to 2025). "It was revealed that miR-193b-3p and -5p regulate malignant phenotypes of lung cancer through the suppression of their common target genes (i.e., CCND1, AJUBA, and HEG1)." (PMID 31262974, 2019). "In the present study, we identified miR-193b-3p and -5p as a new dual-strand tumor suppressor, which inhibits the proliferative and metastatic potential of lung cancer by suppressing common targets, including CCND1, AJUBA, and HEG1." (PMID 31262974, 2019). "Taken together, we demonstrate that miR-193b is a new dual-strand tumor suppressing miRNA and their common target genes (i.e., CCND1, AJUBA, and HEG1) are potential targets for the treatment of lung cancer." (PMID 31262974, 2019). "The Wnt/β-catenin pathway plays a significant role in lung cancer, and currently, there is no research on its regulatory relationship with AJUBA in lung cancer." (PMID 40240814, 2025). "However, the biological functions of AJUBA in lung cancer have not yet been revealed." (PMID 40240814, 2025). "The relationship between AJUBA and Hippo/YAP in lung cancer has not been reported until now." (PMID 40240814, 2025).
prostate carcinoma (3 papers, 2017 to 2022). A carcinoma that arises from epithelial cells of the prostate gland. "Recently, miR-193a-3p was also shown to be androgen-induced and overexpression of miR-193a-3p promotes CRPC cell proliferation by targeting Ajuba LIM Protein (AJUBA), which is repressed in metastatic prostate cancer tissues." (PMID 28783103, 2017).
colon adenocarcinoma (2 papers, 2020 to 2022). "Meanwhile, AJUBA expression was positively correlated with cancer-associated fibroblasts in many human cancers, such as breast invasive carcinoma, colon adenocarcinoma, brain lower-grade glioma, lung adenocarcinoma (LUAD), and ovarian serous cystadenocarcinoma (OV)." (PMID 35898403, 2022). "Then, we interrogated TCGA database and found that SCIB was not significantly up‐regulated in colon adenocarcinoma, but AJUBA was." (PMID 32681581, 2020).
esophageal squamous cell carcinoma (2 papers, 2016 to 2019). Esophageal squamous cell carcinoma (ESCC) is a type of esophageal carcinoma (EC) that can affect any part of the esophagus, but is usually located in the upper or middle third. "We previously identified AJUBA as a putative cancer gene in esophageal squamous cell carcinoma (ESCC)." (PMID 27172796, 2016). "AJUBA promotes the migration and invasion of esophageal squamous cell carcinoma cells (ESCC) through the up-regulation of matrix metalloproteinase 10 (MMP10) and MMP13 expression in ESCC." (PMID 31262974, 2019).
gastric cancer (2 papers, 2019 to 2023). A primary or metastatic malignant neoplasm involving the stomach. "The selection of target proteins was guided by overexpression data obtained from gastric cancer cell lines, specifically focusing on genes such as AJUBA, CD80 and NOLC1." (PMID 37765273, 2023).
glioma (2 papers, 2021 to 2025). A benign or malignant brain and spinal cord tumor that arises from glial cells (astrocytes, oligodendrocytes, ependymal cells). "For example, miR‐433‐3p inhibits the biological functions and malignant progression of gliomas by targeting and inhibiting the expression of AJUBA." (PMID 40900300, 2025).
head and neck cancer (2 papers, 2022). A primary or metastatic malignant neoplasm affecting the head and neck.
malignant mesothelioma (2 papers, 2016 to 2022). A malignant neoplasm of the pleura or peritoneum, arising from mesothelial cells. "In contrast, AJUBA negatively regulates YAP activity through the LATS family to suppress cell proliferation in malignant mesothelioma." (PMID 35898403, 2022). "In addition, AJUBA localized to the nucleus of normal mouse lung epithelial cells and mainly localized to the cytoplasm of tumor tissues of malignant mesothelioma." (PMID 27172796, 2016).
thyroid cancer (2 papers, 2022 to 2023). "Although numerous studies have demonstrated that AJUBA acts as an oncogene or tumor suppressor in different cancer types, the function of AJUBA in thyroid cancer remains unclear." (PMID 37188179, 2023).
embryonal carcinoma (1 paper, 2016). A non-seminomatous malignant germ cell tumor characterized by the presence of large germ cells with abundant cytoplasm resembling epithelial cells, geographic necrosis, high mitotic activity, and pseudoglandular and pseudopapillary structures formation. "The overexpression of full-length AJUBA or of the AJUBA preLIM domain increased the proliferation of P19 embryonal carcinoma cells, whereas overexpression of the three LIM domains of AJUBA reduced cell growth." (PMID 27172796, 2016).
endometriosis (1 paper, 2021). The growth of functional endometrial tissue in anatomic sites outside the uterine body. "AJUBA is a negative regulator of the Hippo signaling pathway, which promotes cell proliferation and inhibits apoptosis in endometriosis." (PMID 33901012, 2021).
esophageal tumor (1 paper, 2016). "The AJUBA protein levels were then detected by IHC in a tissue microarray (TMA) containing 81 primary esophageal tumor tissues and 60 corresponding non-tumor tissues from the same cohort as that of the RNA microarray." (PMID 27172796, 2016).
gastric tumor (1 paper, 2023). "The highest gene expression levels in the gastric tumor dataset were observed for AJUBA (1.44 × 1014), GPNMB (1.11 × 1014) and CD80 (1.09 × 1014)." (PMID 37765273, 2023).
mesothelioma (1 paper, 2017). A usually malignant and aggressive neoplasm of the mesothelium which is often associated with exposure to asbestos. "More recently, studies of YAP modulation by the LIM‐domain protein AJUBA, a binding partner of LATS2, found that mesothelioma cells frequently showed loss of AJUBA expression, which contributes to aberrant YAP activation." (PMID 28470935, 2017).
osteosarcoma (1 paper, 2023). A usually aggressive malignant bone-forming mesenchymal neoplasm, predominantly affecting adolescents and young adults. "In osteosarcoma cells, PRMT5 is relocalized in the nucleus by the transcription factor SNAIL and its corepressor AJUBA." (PMID 37458145, 2023).
paraganglioma (1 paper, 2022). A benign or malignant neoplasm arising from paraganglia located along the sympathetic or parasympathetic nerves. "In contrast, AJUBA expression was low in KICH, LAML, LUAD, pheochromocytoma and paraganglioma (PCPG), PRAD, SKCM, testicular germ cell tumors (TGCT), UCEC and uterine carcinosarcoma (UCS) (p < 0.05)." (PMID 35898403, 2022).
squamous cell carcinoma (1 paper, 2025). A carcinoma arising from squamous epithelial cells. "AJUBA was highly expressed in tumor cells in 73.47% (72/98) of adenocarcinomas and in 61.11% (55/90) of squamous cell carcinomas." (PMID 40240814, 2025).